GABRA3 (gamma-aminobutyric acid type A receptor subunit alpha3)
Diseases named in the same sentence as GABRA3 in open-access papers (continued):
Sharing a sentence is not in itself a finding about the gene and the disease.
mental disorder (2 papers, 2008 to 2022). A disease that has its basis in the disruption of mental process. "The core targets of SHR during the treatment of mental disorders were GABRA1, GABRA2, GABRA3, GABRA5, and GABRA6, involving synaptic transmission and transmembrane movement." (PMID 39280954, 2022).
migraine (2 papers, 2008 to 2013). "Additionally, in the female group we have found an increased risk conferred by the G allele of GABRA3 rs2131190, for migraine susceptibility (OR=1.53, 95%CI: 1.01-2.30; p = 0.043), but that did not remain significant after multiple testing correction." (PMID 24040174, 2013). "On the other hand the CT genotype of rs3902802 and the GA genotype of rs2131190 of GABRA3 gene were associated with a decreased risk for migraine (CT-OR: 0.41; 95% CI: 0.21-0.78, p=0.006; GA-OR: 0.53; 95% CI: 0.32-0.88, p=0.013), that also remained significant after Bonferroni correction." (PMID 24040174, 2013). "We analyzed the distribution of allelic, genotypic and haplotypic frequencies of twenty-three SNPs localized in the GABRE, GABRA3 and GABRQ genes to explore the role of these genes in migraine susceptibility using a case-control approach." (PMID 24040174, 2013). "Regarding the genotypic analyses a set of interesting results reinforced the role of two genes (GABRA3 and GABRQ) in migraine." (PMID 24040174, 2013). "Prior linkage studies have reported mapping of a migraine gene to chromosome Xq 24–28, a region containing a cluster of genes for GABA A receptors (GABRE, GABRA3, GABRQ), which are potential candidate genes for migraine." (PMID 19087248, 2008).
absence seizures (1 paper, 2021). "GABRA3 causes frequent prominent epileptic spasms and atypical absence seizures." (PMID 34414144, 2021).
cleft lip (1 paper, 2020). Congenital defect in the upper lip where the maxillary prominence fails to merge with the merged medial nasal prominences. "Notably, loss-of-function variants in GABRA3, encoding the α3-subunit of the GABAA receptor, have been associated with a DEE including dysmorphic features and a cleft lip." (PMID 32282878, 2020).
colon adenocarcinoma (1 paper, 2022). "Ling Yan and colleagues showed that overexpression of GABRA2, GABRA3, GABRB3, GABRG2, GABRG3, GABRD, and GABRE might be diagnostic for colon adenocarcinoma." (PMID 35565356, 2022).
esophageal cancer (1 paper, 2018). A primary or metastatic malignant neoplasm involving the esophagus. "Furthermore, DUXAP8 is positively related to MAGEA4, GABRA3 expression, and negatively related to INPP5A, TIMP4 expression in esophageal cancer; LINC00460 is positively related to ITGA3, LAMC2 expression, and negatively related to FOXO4, KLF15 expression in esophageal cancer." (PMID 29926523, 2018). "Similarly, we also found that knockdown of DUXAP8 could impair esophageal cancer cells proliferation and invasion, and DUXAP8 expression is positively related to oncogenes MAGEA4 and GABRA3 expression, but negatively related to tumor suppressors INPP5A and TIMP4." (PMID 29926523, 2018).
ischemia (1 paper, 2025). A hypoperfusion of the BLOOD through an organ or tissue caused by a PATHOLOGIC CONSTRICTION or obstruction of its BLOOD VESSELS, or an absence of BLOOD CIRCULATION. "Namely, the peptide reduced the expression of many genes (e.g., P2rx6, Gabra3, Grik4, Oprl1, Glra2, Crhr1, Hrh1, Chrm5, Grik1) related to the neurosignaling system and whose expression was not significantly changed by ischemia itself." (PMID 40650034, 2025).
lung squamous cell carcinoma (1 paper, 2016). "In addition, expression of GABRA3 mRNA in lung squamous cell carcinoma was higher than in matched adjacent non-tumor tissues (t = 4.219, P = 0.0007)." (PMID 27081042, 2016).
lymph node metastasis (1 paper, 2016). "Statistical analyses revealed that levels of GABRA3 protein correlated significantly with TNM clinical stage (P < 0.001), lymph node metastasis status (P < 0.001) and patient survival (P = 0.042)." (PMID 27081042, 2016).
Lymphatic Metastasis (1 paper, 2016). Transfer of a neoplasm from its primary site to lymph nodes or to distant parts of the body by way of the lymphatic system. "Levels of GABRA3 expression were higher in patients with lymphatic metastasis than without it." (PMID 27081042, 2016).
Nystagmus (1 paper, 2026). Rhythmic, involuntary oscillations of one or both eyes related to abnormality in fixation, conjugate gaze, or vestibular mechanisms. "Additionally, higher rates of visual impairment and nystagmus were seen in the GABRA3 GOF group, likely related to the restricted distribution of the α3 subunit in the cerebral cortex, including the occipital cortex." (PMID 41289009, 2026).
psychosis (1 paper, 2023). "HAL could have an effect on psychosis by regulating Gabra3 mRNA expression in the hippocampus." (PMID 37860710, 2023).
Rett syndrome (1 paper, 2024). A severe neurodevelopmental disorder affecting the central nervous system. "In humans, GABRA3 is associated with fetal brain development and is considered a candidate gene for Rett syndrome, a neurodevelopmental disorder that primarily affects females." (PMID 39300329, 2024).
schizophrenia (1 paper, 2021). A major psychotic disorder characterized by abnormalities in the perception or expression of reality. "When counting double-labelled GABRA3+/TH+ and single-labelled GABRA3−/TH+ neurons in 3 control and 3 high inflammatory/schizophrenia cases, we identified GABRA3 expression in 98% of TH+ neurons, irrespective of diagnostic group." (PMID 34174930, 2021). "When stratifying by inflammation, only GABRA3 mRNA exhibited more pronounced changes in high compared to low inflammatory subgroups in schizophrenia." (PMID 34174930, 2021). "We sought to determine relative levels of GABRA1, GABRA2, GABRA3, and GABRA5 mRNAs, GABRA3 protein levels, and to determine cellular location of GABRA3 protein in the midbrain in schizophrenia." (PMID 34174930, 2021). "When analysed by inflammatory subgroup, lower levels of GABRA3 mRNA in the midbrain were only found in the high inflammatory/schizophrenia subgroup." (PMID 34174930, 2021). "The GABAA α3 subunit is expressed on the dopaminergic neurons of the SNpc, and we showed, similar to rat midbrain, 98% of dopaminergic neurons in the human midbrain have GABRA3 immunoreactivity in both controls and schizophrenia cases." (PMID 34174930, 2021). "GABRA3 mRNA in the low inflammatory/schizophrenia subgroup was not significantly different to the control group (p = 0.181)." (PMID 34174930, 2021). "In addition, we found that GABRA3 and GABRA2 mRNAs were highly positively correlated with TH and DAT mRNAs in schizophrenia cases but not controls." (PMID 34174930, 2021).
squamous cell carcinoma (1 paper, 2024). A carcinoma arising from squamous epithelial cells. "All squamous cell carcinoma tumors express a distinct set of GABR genes that are not expressed in normal tissue, including GABRE and GABRA3, while adenocarcinomas show a distinct gene expression signature for a subset of patients or, otherwise, the expression of GABR genes broadly." (PMID 39335139, 2024).
tumor (17 papers, 2016 to 2025). "Our results suggest that miR-92b-3p acted as a tumor suppressor by targeting Gabra3-associated oncogenic pathways; these results provide novel insight into future treatments for PC patients." (PMID 29078789, 2017). "We revealed that BZDR-mediated BRCA signaling pathways through GABRA3-ECMs, which promotes metastasis, probably through immune modulation and changes in the tumor microenvironment." (PMID 40583063, 2025). "We decided to verify the association between hypomethylation/activation of CT-GABRA3 and hypermethylation of GABRA3 in this tumor type." (PMID 34462486, 2021). "In contrast, the reduction in GABRA3 protein levels, due to lower stability of unedited RNA, results in the loss of function which confers an aggressive phenotype to GBM tumor." (PMID 33062411, 2020). "Existing studies have shown that GABRA3 is significantly up-regulated in tumor tissues and can regulate tumor proliferation, invasion and metastasis through AKT-mTOR." (PMID 33681288, 2020). "In this study, we reveal the tumor suppressive nature of editing of GABRA3 in glioma which stresses on the requirement for the gene to be edited in normal scenario." (PMID 33062411, 2020). "In the present study, we found that increased Gabra3 levels were tightly correlated with increased tumor sizes, accelerated lymph node metastasis and advanced TNM stages and poor prognosis in PC patients." (PMID 29078789, 2017). "Here, we provide evidence that miR-92b-3p acted as a tumor suppressor in PC by regulating Gabra3 expression." (PMID 29078789, 2017). "Correspondingly, correlations between reduced Gabra3 expression levels and smaller tumor sizes and lower metastasis rates and TNM stages were also identified in 82 PC patients." (PMID 29078789, 2017). "At the time of diagnosis, the tumor cells had four distinct SNVs in USP54, GABRA3, KRAS and SETD2, while the relapsed tumor acquired four additional unique mutations in MYH7, NYNRIN, ODZ1 and ZIC3." (PMID 26527318, 2016). "As Gabra3 appeared to be more highly expressed in metastatic tissues than in primary tumours, we assessed the contribution of Gabra3 to cell migration and invasion." (PMID 26869349, 2016). "When the popliteal lymph nodes were enucleated and fixed 5 weeks later, we found more luciferase-positive tumor cells within lymph nodes from mice injected with GABRA3-overexpressing cells than with vector-control cells." (PMID 27081042, 2016). "For example, CCNI and GABRA3 are edited to inhibit tumor cell growth, invasion and migration." (PMID 37328893, 2023). "CCNI, GABRA3 after the editing can inhibit tumor cell growth, invasion and migration." (PMID 37328893, 2023). "Interestingly, GABRA3 and miR-92b-3p co-overexpression attenuated the tumor inhibitory role of miR-92b-3p, as shown by increased proliferation, migration and invasion in both AsPC-1 and SW1990 cells." (PMID 29078789, 2017). "GABRA3 expression and tumor stage, including lymph node involvement, were highly correlated." (PMID 27081042, 2016). "Multivariate Cox regression tests further demonstrated that Gabra3 expression associated with survival is independent of other tumour characteristics including tumour stage." (PMID 26869349, 2016). "Moreover, lymph nodes from mice injected with GABRA3-silenced cells had fewer luciferase-positive tumor cells." (PMID 27081042, 2016). "This may be due to insufficient sample size, or it could reflect the relation between GABRA3 expression and tumor stage." (PMID 27081042, 2016). "Thus, GABRA3 editing in glioma may lead to decrease in the protein which might be responsible for the aggressive tumor phenotype but this requires further validation in future." (PMID 33062411, 2020). "We revealed that BZDRs target the GABRA3-ECM signaling pathways to promote cancer advancement through immune modulators and changes in the tumor microenvironment." (PMID 40583063, 2025).
tumor (continued). "The results showed that compared with HSKMC, PODXL2, LRRC17, GABRA3, SCUBE3, and RFLNB were highly expressed in tumor cells, while IGHG2 and HLF were low expressed." (PMID 36155774, 2022). "So far, no studies have shown that these seven genes (IGHG2, PODXL2, LRRC17, GABRA3, SCUBE3, HLF and RFLNB) are directly related to pyroptosis in tumor cells." (PMID 36155774, 2022). "An important issue was to determine if genes other than GABRA3 and GABRQ, and in particular tumor suppressor genes, rely on a similar process of DNA hypomethylation-induced overlapping transcription to become hypermethylated in tumors." (PMID 34462486, 2021). "While studying the human MAGEA6/GABRA3 gene locus, we observed that DNA hypomethylation in tumor cells can lead to the activation of a long transcript (CT-GABRA3) that overlaps downstream promoters (GABRQ and GABRA3) and triggers their hypermethylation." (PMID 34462486, 2021). "Additionally, GABRA3 may not be the only receptor, and crosstalk with the other GABA receptors, such as GABRP may be occuring; alternatively, there could be other regulatory genes that may also contribute to ECM-associated BRCA tumor progression." (PMID 40583063, 2025). "Lack of GABRQ/GABRA3 and PTPRO/RERG promoter hypermethylation was indeed observed in a fraction of tumor samples that nevertheless produced the overlapping transcripts." (PMID 34462486, 2021). "Correspondingly, levels of GABRA3 protein were markedly higher in LUAD cell lines than in normal human lung epithelial cells, and higher in clinical LUAD tissues than in matched adjacent non-tumor tissues." (PMID 27081042, 2016).
cancer (13 papers, 2013 to 2025). A tumor composed of atypical neoplastic, often pleomorphic cells that invade other tissues. "For example, studies on different types of cancers, including breast, pancreatic and lung, have implicated Gabra3 in the disease progression." (PMID 30930755, 2019). "Specifically, Gabra3 was found to promote cancer cell invasion and migration by activating various inflammatory pathways such as AKT/mTOR and JNK." (PMID 30930755, 2019). "In one of the studies, it was discovered that only the unedited form of Gabra3 had metastatic properties, while A-to-I edited Gabra3 was found to suppress cancer progression." (PMID 30930755, 2019). "Further characterization of Gabra3 signalling pathways will enhance our understanding of its functions in cancer development." (PMID 26869349, 2016). "In contrast, high level GABRA3 gene expression is correlated with cancer cell development, and thus these patients had worse outcome." (PMID 23617850, 2013). "For example, the GABRA3-ECM pathway may be therapeutically manipulated to halt cancer advancement in BZDR-user patients." (PMID 40583063, 2025). "Our previous study demonstrated that Gabra3 plays critical roles in cancer progression." (PMID 29078789, 2017). "Both GABRA3-shRNA and GABRA3-CRISPR/Cas9 in MDA-MB231 cells consistently reduced cell invasion caused by BZDRs (* p < 0.05; ** p < 0.01; *** p < 0.005), confirming that GABRA3 plays a pivotal role in promoting cancer progression in BZDR-mediated cancer signaling, during BRCA progression." (PMID 40583063, 2025). "We next examined the correlation between GABRA3 and the previously identified ECM molecules, based on hints that ECMs are involved in cancer progression." (PMID 40583063, 2025). "Results showed that GABRA3, SLC6A3, GABRQ, SCN4A, and GABRG3 were overexpressed in cancer compared with normal liver tissues." (PMID 35401884, 2022). "Furthermore, based on retrospective studies we found that among 16 GABA receptors, GABRA3 was significantly upregulated during BRCA advancement, whereas GABRP was downregulated in the later stages of cancer." (PMID 40583063, 2025). "Therefore, based on these results, we suggested that GABRA3, SLC6A3, GABRQ, and SCN4A might be cancer-specific targets of Carvacrol which were further screened in the subsequent study." (PMID 35401884, 2022). "The GRIK2 Q/R, Y/C, and GABRA3 I/M sites emerged as sites with a remarkable editing decrease in GBM (with an editing drop ranging from − 82 to − 74% Δ medians) followed by GLI1 R/G site (− 27% Δ medians), the latter playing a key role in modulating the Hedgehog (HH) signaling in cancer." (PMID 30760294, 2019). "We found that a 7-day treatment regime with these BZDRs (regarded as prolonged treatment under in vitro condition), significantly upregulated GABRA3 in both non-carcinoma MCF10A and carcinoma cells, MCF7 and MDA-MB231." (PMID 40583063, 2025). "Results showed that expressions of DRD1, GABRA3, SLC6A3, GABRQ, and SCN4A in cancer were significantly higher than those in noncancer tissues." (PMID 35401884, 2022).
neurodevelopmental disorder (2 papers, 2024 to 2026). A behavioral and cognitive disorder with onset during the developmental period that involves impaired or aberrant development of intellectual, motor, or social functions. "For the pathogenic GABRA3 variants, a distinct and consistent sex-linked association of neurodevelopmental disorders is observed, which correlates with the functional analysis findings and is not suggestive of random X inactivation in females." (PMID 41289009, 2026).
GABRA3 also shares sentences with these, for which no sentence is quoted: glioblastoma (2 papers); adenocarcinoma (1); astrocytoma (1); cognitive deficits (1); Epileptic spasm (1); heroin addiction (1); infection (1); liver cancer (1); neuroblastoma (1); neurological disorders (1); nicotine addiction (1); non-small cell lung carcinoma (1); sarcoma (1).